FADD (Fas associated via death domain)
Diseases named in the same sentence as FADD in open-access papers (continued):
Sharing a sentence is not in itself a finding about the gene and the disease.
infection (35 papers, 2008 to 2026). The state of being infected such as from the introduction of a foreign agent such as serum, vaccine, antigenic substance or organism. "Lastly, integrating both pathway and cell models in a multicellular-multiscale model helped reveal the impact of mutations of FADD and p38 on the cellular death of epithelial cells upon infection and the recruitment of immune cells." (PMID 38414974, 2023). "The opposing roles of TRADD and FADD at different infection stages reveal a sophisticated spatiotemporal regulatory strategy employed by Eimeria." (PMID 41463813, 2025). "Further investigations revealed that TRADD and FADD exhibit opposing functions at different stages of infection." (PMID 41463813, 2025). "It has been reported that FADD−/− MEFs are highly sensitive to infection by many RNA viruses, including influenza virus, VSV and EMCV, due to defective interferon production." (PMID 38650851, 2024). "Meanwhile, our research provides a reference dataset for in-depth studies on the molecular mechanisms of (TLR1-2) - MyD88 - FADD - Caspase 8 mediating apoptosis pathway in bony fish after the bacterial pathogen infection." (PMID 37056759, 2023). "Two DEGs exhibited a time-specific expression pattern in both infection groups: reduction of FADD at 12 hpi and elevation of JunB at 6 hpi." (PMID 35234615, 2022). "Geneslocated among them partake in infection initiation (espH),amino acid biosynthesis (asnB1), acyl-CoA and fatty acidsbiosynthesis ( fadD)." (PMID 36694719, 2022). "We therefore propose that RIPK3 platform activity-dependent and FADD-mediated apoptosis partially protect laboratory mice against IAV-infection in vivo." (PMID 33976111, 2021). "In contrast, FADD, albeit abundant, appeared to be expressed constitutively throughout the studied time points of infection." (PMID 28919893, 2017). "BAK, BAX, FADD, IKKα and all showed decreases in abundance in Makona or Ecran infected A549 and NPro cells compared with mock infection." (PMID 28240256, 2017). "It was observed that the levels of IPS-1, TRAF 6 and active Caspase 8 were significantly increased both after 12 and 24 h post infection, whereas the levels of phosphoIKKα/β and FADD were only increased after 24 h (p<0.05)." (PMID 21738791, 2011). "Through TUNEL assay, flow cytometry, and apoptotic pathway analysis, Our analysis revealed that H5N6 AIV infection markedly upregulates apoptotic genes such as Fas, FADD, caspase-8, BAK, cytochrome c, APAF1, caspase-9, and caspase-3 (P < 0.05), thereby promoting apoptosis in DEFs." (PMID 41992349, 2026). "Our results show that TiLV-infected E-11 cells exhibit significant changes in the proteins involved in the JAK–STAT and FADD–TRAF pathways during early infection, which further activate NOD-signaling and apoptotic pathways, leading to the viral replication and cell death." (PMID 39995988, 2025). "The expression profiling of TLR signaling pathway genes after pathogen stimulation showed that the infection of pathogens induced the activation of (TLR1-2) - MyD88 - FADD - Caspase 8 involved signaling pathway, and inhibits the spread of bacteria in the body through cell apoptosis." (PMID 37056759, 2023). "Furthermore, the interaction between RIP1 and FADD/Caspase-8 was notably enhanced after AC infection." (PMID 33683530, 2022). "Altogether, TNF-α elicited RIP1/FADD/caspase-8-mediated apoptosis of astrocytes upon AC infection." (PMID 33683530, 2022). "Interestingly, compared with wild type cells, the formation of syncytia also increased in FADD-/- Jurkat cells post-infection." (PMID 24714696, 2014). "Indeed, HIV-1-infection-induced apoptosis in FADD-/- Jurkat cells dramatically decreased, while necroptosis significantly increased, compared to that in wild-type Jurkat cells." (PMID 24714696, 2014).
infection (continued). "The identification of FadD, FadL, and PlsB in our screen may highlight the importance of remodeling the lipid composition of the V. cholerae membrane during host infection prior to transition into the aquatic environment." (PMID 24385900, 2013). "Gene acs shares sequence similarity with the gene of long chain fatty acid CoA synthetase (FadD), an enzyme involved in lipid synthesis and whose expression may be important at various stages of infection." (PMID 18226222, 2008). "Fas-associated death domain (FADD) and receptor interacting protein kinase 3 (RIPK3): The FADD protein is a key mediator of death receptor-triggered extrinsic apoptosis, which plays a crucial immune regulatory role at the site of infection and prevents excessive inflammation." (PMID 30761136, 2019). "Conversely, the late phase of infection is executed via the convergence of the mitochondrial pathway (driven by Bax activation and MOMP), the death receptor pathway (via FasL and TRADD/FADD signaling), and the amplification of stress signals from the ER." (PMID 41463813, 2025). "Conversely, the late phase of infection is characterized by the convergence of the mitochondrial pathway (driven by Bax activation and MOMP), the death receptor pathway (via FasL and TRADD/FADD signaling), and the amplification of ER stress signals." (PMID 41463813, 2025). "Although modification of TRADD, FADD, and RIPK1 in in vitro reconstitution system and ex vivo epithelial cell infection system has been studied, the in vivo substrate preference of NleB remains elusive." (PMID 32766249, 2020). "All pro- (Casp-8, FADD, BAX, and BAK) or anti-apoptotic (BCL-2 and XIAP) genes tested were down regulated at early time points post-SVA infection (2–4 h p.i.)(p < 0.05 when compared to mock-infected cells)." (PMID 30918505, 2019). "The impairment of dsRNA-induced apoptosis late in infection was controlled by the viral 3C-protease (3Cpro), which disrupted RIPK1-TRIF/FADD /SQSTM1 immune-complexes." (PMID 29449668, 2018). "The enteropathogenic and enterohemorrhagic Escherichia coli T3SS effector NleB inhibits death domain-containing proteins, including FADD and TRADD, leading to reduced NF-κB pathway activation and impaired caspase-8-dependent host cell death during infection." (PMID 28069818, 2017). "During infection, ZBP1 responds to IAV and forms the ZBP1-RIPK3 complex, which then facilitates recruitment of RIPK1 and further forms ZBP1-PANoptosomes with ZBP1/RIPK3/RIPK1/FADD/CASP8 as the main components." (PMID 40568592, 2025). "After infection with A. hydrophila, the transcriptional levels of TLR1, TLR2, caspase 8, MyD88, FADD, TOLLIP isoform 1 and TOLLIP isoform 2 were all significantly up-regulated in the kidney, indicating that bacterial infection induced the activation of TLR signaling pathway in the yellow catfish." (PMID 37056759, 2023). "After infection, mRNA relative expressions of TNFR1 and FADD in the lean-E." (PMID 32685099, 2020). "Considering that NleB could modify the DDs of TRADD, FADD, and RIPK1 in cell culture infection system, it is necessary to determine the target in vivo." (PMID 32766249, 2020). "Therefore, FADD and TRADD are likely to represent genuine targets of SseK proteins during host cell infection." (PMID 28069818, 2017). "Since cellular immune responses were not significantly influenced, we speculate that cFLIP and FADD may modulate the innate immunity to fight the infection, as it has been reported that blocking type I interferon helps control chronic LCMV infection." (PMID 25807052, 2015).
infection (continued). "Infection-induced arginine-GlcNAcylation of FADD and TRADD (but not of the GFP control) was dependent on the SseK proteins: SseK1 modified FADD while both SseK1 and SseK3 induced modification of TRADD." (PMID 28069818, 2017). "In our research, the mRNA expression of FADD and TNF-α which belong to extrinsic pathway were not significantly altered after NNV infection, indicating that it was the intrinsic pathway that was activated in CAB cells post-infection." (PMID 36298739, 2022).
bacterial infections (4 papers, 2007 to 2023). "It was recently reported that dFADD acts in concert with DREDD in immune defenses against bacterial infections, indicating a functional difference in FADD molecules between these species." (PMID 17540041, 2007). "In addition, the H. parasuis fadD1 mutant showed increased sensitivity to quinolone antibiotics, suggesting that if antibacterial agents could be developed against FadD, drug combinations including these agents may more effectively control these bacterial infections." (PMID 28361037, 2017).
dermatitis (4 papers, 2014 to 2021). An inflammatory process affecting the skin. "Collectively, our results show that TNFR1-induced TRADD- and FADD-dependent apoptosis of Sharpin-deficient keratinocytes triggers the chronic proliferative dermatitis phenotype in Sharpincpdm/cpdm mice." (PMID 25443631, 2014).
inflammation (3 papers, 2021 to 2024). Aberrant reaction of the microcirculation characterized by movement of fluid and leukocytes from the blood into extravascular tissues. "The findings that RIPK1-RIPK3-MLKL signaling is required for the exacerbated HDM-induced lung inflammation in FADDAEC-KO mice suggested that FADD deficiency sensitized AECs to necroptosis after exposure to HDM, which resulted in exaggerated inflammatory responses." (PMID 34045680, 2021). "However, our previous work in mice lacking FADD in intestinal epithelial cells (IECs) showed that TNFR1 cooperates with ZBP1 to induce necroptosis-mediated gut inflammation, revealing an intricate interplay between TNFR1 and ZBP1 in causing IEC necroptosis." (PMID 38849574, 2024).
cardiovascular diseases (1 paper, 2025). "Our findings provide new insights into hypoxia-mediated necroptosis, suggesting that targeting SUMOylation and FADD has the potential to prevent and treat vascular ischemic injury and related cardiovascular diseases." (PMID 39984463, 2025). "Taken together, our research has uncovered a new process by which SUMOylation of FADD regulates hypoxia-induced necroptosis in endothelial cells, providing potential therapeutic targets for hypoxia-related cardiovascular diseases." (PMID 39984463, 2025).
hematologic malignancies (1 paper, 2024). "Interleukin 1 receptor associated kinase 1 (IRAK1) is an emerging therapeutic target in hematologic malignancies, and it has been suggested that IRAKs participate in regulatory interactions with FADD." (PMID 38412862, 2024).
hematological cancer (1 paper, 2014). "Edelfosine has been reported to induce apoptosis in a variety of hematological cancer cells through the recruitment into lipid rafts of extrinsic apoptotic pathway molecules forming clusters of Fas/CD95 death receptor and downstream signaling molecules, including FADD and procaspase-8." (PMID 25593994, 2014).
neurodegenerative disease (1 paper, 2025). A disorder of the central nervous system characterized by gradual and progressive loss of neural tissue and neurologic function. "Based on the findings from in vivo and in vitro studies, both HMOX1 and FADD genes are considered promising therapeutic targets for neurodegenerative diseases." (PMID 41203125, 2025).
FADD also shares sentences with these, for which no sentence is quoted: acute promyelocytic leukemia (2 papers); acute T-cell leukemia (2); Arthritis (2); esophageal squamous cell carcinoma (2); lung squamous cell carcinoma (2); metabolic disorders (2); Multiple Myeloma (2); myeloid leukaemia (2); thyroid cancer (2); acute myocardial infarction (1); adenocarcinoma (1); apical periodontitis (1); Autoimmunity (1); B-cell acute lymphoblastic leukemia (1); bladder cancer (1); brain diseases (1); breast (1); cardiac hypertrophy (1); cerebral aneurysms (1); cerebrovascular diseases (1); Cirrhosis (1); co-infection (1); Cognitive impairment (1); colon adenocarcinoma (1); colorectal adenocarcinoma (1); coronary heart diseases (1); cortical atrophy (1); Crohn disease (1); cystitis (1); deafness (1).
A further 45 diseases each share a sentence with FADD in 1 paper.